CXCR3 (C-X-C motif chemokine receptor 3)
Diseases named in the same sentence as CXCR3 in open-access papers (continued):
Sharing a sentence is not in itself a finding about the gene and the disease.
lupus (continued). "Such functional lymphoid structures have been described in several autoimmune conditions among which the kidneys of a chemically-induced mouse model of lupus, and they could be the site where CXCR3-expressing early-differentiated plasma cells originate from." (PMID 23520491, 2013). "The anti-CXCR3 antibody level correlated negatively with the total protein level after 2 years of observation (p = 0.03) and with the basic albumin level (p = 0.02) and albumin level after 1 month of observation (p = 0.04) in the systemic lupus erythematosus group." (PMID 39768675, 2024). "Supporting the role of CXCR4 in ASC homing and retention in the BM, even in the pro-inflammatory milieu of the lupus BM20, this receptor was expressed in the majority of BM PC whereas CXCR3 expression was rare on SLE BM PC." (PMID 38429276, 2024). "Supporting the role of CXCR4 in ASC homing and retention in the BM, even in the pro-inflammatory milieu of the lupus BM, this receptor was expressed in the majority of BM PC whereas CXCR3 expression was rare on SLE BM PC." (PMID 37461641, 2023). "Therefore, the enhanced co-expression of CXCR4 and CXCR3 in circulating SLE ASC suggests a strong capability of these cells to migrate into inflamed Lupus kidneys, whether as a primary or a secondary amplifying event." (PMID 37461641, 2023). "Systemic lupus erythematosus mice had a 3 to 5-fold higher renal cortical mRNA expression of lymphocyte-specific CXC chemokines (CXCL9,10,13, and 16) and CXC receptors (CXCR3 and 4) that contribute to SLE pathophysiology." (PMID 31133860, 2019). "Therefore, further studies are required to determine whether CXCR3 is important for LN development and which ligand(s) are critical for the infiltration of CXCR3+ cells to the kidney of lupus-prone mice." (PMID 27403037, 2016). "Thus, early differentiated CD138highMHCII+ rather than terminally differentiated CD138highMHCIIlow plasma cells may be involved in the renal inflammatory injury in lupus, due to CXCR3 expression and IgG secretion." (PMID 23520491, 2013). "We showed that globally reducing FLI-1 levels in a lupus prone mouse strain reduced renal Cxcl9 and Cxcl10 gene expression and renal-infiltrating CXCR3+ T cells, and that FLI-1 can upregulate Cxcr3 promoter activity in T cells." (PMID 37790939, 2023). "In lupus-prone mice, most commonly NZB/W F1 mice and MRL/lpr mice, CXCR3-expressing T cells and plasma cells as activated effector populations in the secondary lymphoid organs are increased during the development of LN." (PMID 27403037, 2016). "In the present study, we investigated the expression of chemokine receptors, CXCR3, CCR5, CCR4, and CCR3, in the surface of probiotic-maturated tolerogenic DCs (matured by L. rhamnosus and L. delbrueckii) with monocyte origin to find the effect of these probiotics on migratory lupus-DC patterns." (PMID 35317107, 2021). "For example, CD40L and CXCR3 are biallelically expressed in T cells isolated from female, but not male, systemic lupus erythematosus (SLE) patients." (PMID 38486287, 2024). "Moreover, urinary mRNA levels of the CXCR3 ligand CXCL10 and CXCR3+ CD4+ T cells in the urine were suggested as non-invasive tools for monitoring the activity in lupus nephritis and might therefore provide a new biomarker for acute nephritis flares in systemic lupus erythematosus patients." (PMID 33598825, 2021).
colon carcinoma (35 papers, 2009 to 2025). "In summary, our results show that CXCR3 expression and activation is associated with tumour-promoting activities on colon cancer cells in vitro, namely proliferation, survival and migration." (PMID 19436305, 2009). "Another previous study has demonstrated that CXCR3 activation with its ligands stimulates colon cancer metastasis." (PMID 40651961, 2025). "Heightened expression of CXCR3 and CXCR4 has been implicated in promoting colon cancer metastasis to draining lymph nodes, thereby correlating with unfavorable prognoses for CRC tumors metastasizing to the liver and lungs." (PMID 39835121, 2024). "Examination of CXCR3 in primary colon cancer tissues revealed high CXCR3 expression in approximately one-third of the tumors, whereas half were positive for CXCR4 expression." (PMID 36479091, 2022). "Given the anti-tumor roles of IL-10 and TGF-β in early stage colon cancer development, we concluded that CXCR3 inhibits early stage colorectal tumorigenesis by attracting both CTLs and Treg cells." (PMID 31775909, 2019). "Some human colon cancer cell lines constitutively express CXCR3 and its expression in the primary tumor lesion significantly correlates with lymphatic invasion and lymph node metastasis." (PMID 30591657, 2018). "In accordance, migration of patient-derived cytotoxic T-cells towards autologous colon cancer cells has been shown to be mediated by CXCR3 expressed on T-cells, and by CXCL11 expressed by tumor cells." (PMID 29163806, 2017). "Overexpression of CXCR3 in human colon cancer cell lines and activation with ligands increases metastasis to the draining lymph nodes." (PMID 25798946, 2015). "Additional studies suggest that CXCR3 activation in colon cancer synergistically enhances CXCR4-mediated tumor cell migration to the lymph nodes, liver, and lungs." (PMID 24259307, 2013). "Kawada et. al demonstrate that expressing CXCR3 in a colon cancer cell line increases in vivo metastasis to the lymph nodes, but not to the liver or lungs." (PMID 24259307, 2013). "For instance, an FPR variant receptor, FPRL1, in monocytic cells and a chemokine GPCR CXCR3 in colon cancer cells have also been shown to up-regulate MMP9." (PMID 20197768, 2010). "Beside its expression on colon cancer cells, CXCR3 is indeed expressed on T lymphocytes, dendritic cells, monocytes, natural killer cells and was reported as an important receptor for the immune response to be optimally executed." (PMID 19436305, 2009). "As a next step, we investigated the relevance of CXCR3 expression levels for colon cancer metastasis to the two main target organs, liver and lung, using two metastatic mouse models." (PMID 19436305, 2009). "We observed a marked difference in the human CXCR3 staining between sections of lung and liver metastases both in the percent of CXCR3-positive colon cancer cells and in the expression intensity within the CRC cells cytoplasm." (PMID 19436305, 2009). "Further elucidating this precise aspect that was beyond the scope of our study, will require approaches performing the specific silencing of CXCR3 on the tumour colon cancer cells." (PMID 19436305, 2009). "Therefore we wondered if tumor growth of MC38 colon cancer would be affected in CXCR3 knockout mice." (PMID 26956047, 2016). "In addition, exogenous expression of CXCR3 in a human colon cancer cell line, increased metastasis of these cells to the draining lymph nodes (DLNs) of injected mice, compared to non-expressing cells." (PMID 25798946, 2015). "On the basis of chemotactic-promoting effect of CXCR3/ligands interactions on CRC cells, we next investigated the contribution of this axis in the implantation of colon carcinoma within lungs and liver by developing a preventive blockade of CXCR3 before tumour cell inoculation into mice." (PMID 19436305, 2009).
colon carcinoma (continued). "Therefore, the CXCR3-positive C26 colon carcinoma cells were pre-treated with 1 μmol l−1 of AMG487 or vehicle for 18 h in vitro before being injected into syngeneic BALB/c mice to generate either pulmonary or liver metastases." (PMID 19436305, 2009). "Although this group recently reported the crucial role played by CXCR3 in the metastatic process of CRC to lymph nodes, the relevance of CXCR3 expression in colon cancer metastasis to liver and lung, which remain the major cause of mortality in this pathology, has not been addressed." (PMID 19436305, 2009). "However, so far, the relevance of CXCR3 expression levels in colon cancer metastasis to liver and lung, which remains the major leading cause of death in this malignancy, has not been investigated." (PMID 19436305, 2009). "Thus, the function of CXCR3 in colon cancer may depend on its cooperation with other expressed chemokine receptors such as CXCR4 and CCR7." (PMID 24259307, 2013). "However, in contrast to the effects on pulmonary metastasis, the extent of liver metastasis was not affected by the preventive CXCR3 antagonism, pointing to the fact that CXCR3 may mediate organ-specific implantation of colon carcinoma in this model." (PMID 19436305, 2009). "Thus, CXCR3 appears to contribute to the progression of colon cancer metastases in the lung." (PMID 19436305, 2009). "CXCR3+ NK-cell and CD8+ T-cell tumoral infiltration, directed by CXCL9 and CXCL10, can delay primary tumor growth in MC38 colon carcinoma and TC-1 epithelial carcinoma mouse models when treated with heterodimeric IL-15." (PMID 36030223, 2022). "Flow cytometric analysis of surface protein expression on CT-26 cells demonstrated clear-cut expression of CXCR2, CXCR3, CXCR4 and CXCR5, suggesting a potential role of CXC chemokines in colon cancer cell biology." (PMID 34115261, 2021). "Herein, it was found that the murine colon cancer cell line CT-26 expressed several of the pro-inflammatory chemokine receptors in the CXC chemokine family, including CXCR2, CXCR3 and CXCR4." (PMID 34115261, 2021). "C1 (Tumor-Treg) showed 112 DEGs between colon cancer and rectal cancer, such as TNF and CXCR3, which were up-regulated, while CXCR6 and CCR6 were down-regulated in colon cancer in comparison to that of rectal cancer." (PMID 33584715, 2020). "Forced expression of CXCR3 on colon cancer cells promoted lymph node metastasis, and CXCL10 enhanced invasive and migratory capacities of colon cancer cells in vitro." (PMID 29163806, 2017). "Furthermore, the CXCL-10/CXCR3 axis was shown to enhance tumorigenicity and EMT induction in colon cancer cells." (PMID 40447617, 2025). "Although CXCR3 plays a crucial role in lymph node metastasis, its role in colon cancer metastasis to the liver and lungs has not been fully elucidated." (PMID 36479091, 2022). "However, CXCL4 expression in MC38 colon cancer in mice was shown to coincide with the suppression of a CD8+ T cell influx and promotion of Treg responses via CXCR3, and accelerated tumor growth." (PMID 34503058, 2021). "CXCR3 has been found expressed in colon cancer epithelium but has not been detected in normal colonic epithelium." (PMID 30591657, 2018). "In addition, tumor infiltrating CD56brightNK cells from breast and colon carcinomas highly express CD9 and CXCR3, similar to the reported exclusive expression of these cell surface markers by decidual NK cells as opposed to pNK cells of both subsets." (PMID 26079948, 2015). "Some colon cancers also constitutively express CXCR3, and patients that express CXCR3 in tumors experience worse prognosis than those without CXCR3." (PMID 24259307, 2013). "Preventive systemic treatment with AMG487, a small molecular weight antagonist of CXCR3, significantly reduces metastasis of colon cancer cells to the lung without affecting that to the liver." (PMID 19436305, 2009).
colon carcinoma (continued). "Similar to human breast and colon cancer cell lines, we found that growing BOWES cells under conditions of cellular stress (media without serum, incubated at 37°C with 8% CO2, hereafter referred to as stressed cultures) increased the proportion of cells expressing CXCR3." (PMID 25798946, 2015). "Moreover, both motility and growth responses of the colon cancer cells are considerably reduced by AMG487, a small molecular antagonist of CXCR3, thus indicating that CXCR3 may play a major role in the spread and progression of colon cancer metastases in vivo." (PMID 19436305, 2009).
ovarian carcinoma (33 papers, 2006 to 2025). A malignant neoplasm originating from the surface ovarian epithelium. "The malfunction of osteoclasts, caused by ovarian cancer long noncoding RNA (OC-lncRNA), is mediated through the OC-lncRNA-miR-221-5p CXCR3 axis." (PMID 39139310, 2024). "Differential expression of the three CXCR3 spliced variants was also reported in patients with ovarian carcinoma." (PMID 29379506, 2017). "Moreover, it has been proposed that an increasing percentage of CXCR3 variants over time might be an essential component of endometriosis-related carcinogenesis in patients with ovarian cancer." (PMID 40373032, 2025). "CXCR3, in turn, is responsible for the recruitment of tumour-suppressive T-cells to the ovarian cancer tumour microenvironment." (PMID 40579444, 2025). "In ovarian cancer, CXCR3 facilitates the migration of tumor-infiltrating lymphocytes, including Tregs, promoting anti-tumor immune responses." (PMID 39000453, 2024). "In order to therapeutically exploit our results, ICB should be combined with therapies that induce the expression of CXCR3 chemokines in the ovarian cancer tumour microenvironment." (PMID 35314795, 2022). "CXCL10 is abundant in ascites fluid from ovarian cancer patients, where it is involved in the CXCR3-mediated migration of cancer cells and specific T-cell subsets." (PMID 34200333, 2021). "The expression of CXCR3/4/7 mRNA in ovarian cancer tissues was higher than that in normal ovarian tissues, and the expression of CXCR4 was the highest (fold change = 306.413, P < 0.05)." (PMID 33829065, 2021). "A significant increase in the number of NK cells and CD8+ T cells expressing CXCR3 is shown in ovarian cancer." (PMID 31696204, 2019). "CXCR3+ Treg have been isolated from the TME of ovarian cancer and HCC; increased CXCR3+ Treg presence in the TME has been correlated to a blunted effector response, and HCC tumor recurrence following transplantation." (PMID 31681327, 2019). "CXCR3+ Treg cells selectively accumulate in ovarian cancer and block the interactions between CXCR3 and its ligands CXCL9, CXCL10, and CXCL11, thereby suppressing tumor growth." (PMID 29463952, 2017). "We next explored the function of CXCR3 in ovarian cancer using the two well-established epithelial ovarian cancer (EOC) cell lines OVCAR3 (HGSC) and SKOV3 (clear cell ovarian cancer) as in vitro models." (PMID 28504691, 2017). "Our results advocate further studies assessing CXCR3 as a potential target for ovarian cancer therapy." (PMID 28504691, 2017). "This study in ovarian cancer patients identifies CXCR3 expressed by tumor cells as a novel independent prognostic marker of reduced PFS and OS." (PMID 28504691, 2017). "We demonstrate that CXCR3 is expressed at the invasive front of ovarian carcinomas and overexpressed in intraabdominal metastases." (PMID 28504691, 2017). "Ovarian cancer tissue revealed the highest CXCR3-alt expression (CXCR3-alt expression in cancer > endometriosis > normal tissue)." (PMID 29379506, 2017). "In conclusion, our analyses in primary patient samples indicate that CXCR3 is a driver of tumor cell migration toward the peritoneal environment in human ovarian cancer." (PMID 28504691, 2017). "For example, in human ovarian carcinomas, selective accumulation of Treg cells expressing high levels of chemokine receptor CXCR3 was noted." (PMID 23874336, 2013). "In human ovarian carcinomas, CXCR3+ Treg cells were reported to be abundantly represented in the majority of tumor-Treg cells and they co-express Helios." (PMID 23874336, 2013). "Bioinformatics analysis of the expression of the C-X-C motif chemokine receptors (CXCRs) in ovarian cancer indicated higher expression of CXCR3, -4, -7 mRNA and different expression of CXCR1, -2, -3, -4, -7 mRNA in different pathological types of ovarian tumors." (PMID 38248751, 2023).
ovarian carcinoma (continued). "Although CXCR3 chemokine expression has not yet been compared as a function of BRCA mutation status in human ovarian cancer, our observation is sufficient to explain the higher number of tumour-infiltrating lymphocytes in BRCA-mutated tumours." (PMID 35314795, 2022). "Finally, the CXCR3-positive human ovarian cancer cell lines OVCAR-3, OV-MZ-6, CAOV-3 and SKOV-3 were treated with 100 ng/mL recombinant human CXCL9 for 72 h and lysed for western blot analysis." (PMID 35314795, 2022). "To address this hypothesis in humans, we explored expression, function and prognostic impact of tumor cell CXCR3 in ovarian cancer patients." (PMID 28504691, 2017). "Likewise, CXCR3+ Treg cells were isolated from human ovarian carcinomas and shown to suppress Teff proliferation and IFN-γ production ex vivo." (PMID 25946021, 2015). "Additionally, overexpression of CXCR3 is significantly associated with the tumor grade and lymph node metastasis, suggesting a role for CXCL11/CXCR3 in promoting ovarian carcinoma metastasis." (PMID 24384839, 2013). "The CXCR3/4/7 could be potential therapeutic targets in ovarian cancer." (PMID 38248751, 2023). "Thus, activation of the adaptive immune response seems to be the major mechanism behind the protective nature of CXCL9 in ovarian cancer, possibly more important than chemotactic retention of CXCR3-positive tumour cells in the primary tumour as proposed before." (PMID 35314795, 2022). "CXCL11 is highly expressed in the immunoreactive subtype, and its ligand CXCL11 and receptor CXCR3 characterize this subtype, with the CXCL11-CXCR3 signaling pathway being a therapeutic target for ovarian cancer." (PMID 39680618, 2024). "CXCR3 and CXCR4 play crucial roles in mobilizing Treg cells to tumor locations in various cancers, including ovarian cancer, hepatocellular carcinoma (HCC), breast cancer, and lymphoma." (PMID 39000453, 2024). "Several unsupervised studies, aiming to define the molecular subtypes of ovarian cancer by gene expression profiling, univocally identified CXCL9 and the other CXCR3 chemokines as marker genes of an inflammation-enriched subtype." (PMID 35314795, 2022). "The results of this study indicate that CXCR3/4/7 are potential targets for the treatment of ovarian cancer, and CXCR2/4/5/6/7 are new markers for the prognosis of ovarian cancer." (PMID 33829065, 2021). "The results showed that CXCRs were expressed in both cell membrane and cytoplasm of ovarian cancer tissues, among which CXCR4 expressions were the highest, and CXCR3, CXCR5, CXCR6, and CXCR7 were expressed in different degrees." (PMID 33829065, 2021). "The results showed that the expression of CXCR3, CXCR4, and CXCR7 mRNA in ovarian cancer tissues was significantly higher than that in normal ovarian tissues (P < 0.05)." (PMID 33829065, 2021). "CXCR3/4/7 are potential therapeutic targets, and CXCR2/4/5/6/7 are new markers for the prognosis of ovarian cancer." (PMID 33829065, 2021). "Ovarian cancer cell-derived lymphotoxin up-regulates CXCL11 secretion by CAFs; CXCL11, on the other hand, activates chemokine receptor CXCR3 on ovarian cancer cells and promotes their proliferation and motility." (PMID 26751490, 2016). "We compared the mRNA expression of CXCR3, CXCL-10, CXCR4, CXCL-12, IL-4, and IL-10 in tissues of benign and malignant ovarian tumors by qRT-PCR method and evaluated serum IL-10 and CA-125 content of these patients by ELISA during one year." (PMID 25999622, 2015). "In the current study, we performed a comparative analysis on mRNA expression of CXCR3, CXCL-10 (IP-10), CXCR4, CXCL-12 (SDF-1α), IL-4 (interleukine-4) and IL-10 in tissues of benign and malignant ovarian tumors by the qRT-PCR method." (PMID 25999622, 2015). "These T-regulatory cells accumulate in the ovarian cancer microenvironment due to the release CXCL10, a ligand for CXCR3, by the cancer cells." (PMID 24384839, 2013).